CCL2 (C-C motif chemokine ligand 2)
Diseases named in the same sentence as CCL2 in open-access papers (continued):
Sharing a sentence is not in itself a finding about the gene and the disease.
tumor (continued). "Influenced by the tumor microenvironment, and through the production of specific chemokines such as CCL-2, CCL-7 or CCL-12, MSCs are able to recruit CCR2 expressing monocytes to tumor sites, promoting the local concentration of macrophages and tumor growth." (PMID 35214113, 2022). "While CD4+ memory resting T cells contribute most T-cells within the tumour microenvironment (TME), their presence is highly influenced by CCL2, ANG, CHI3L1, IL-6 and IL-8." (PMID 36430641, 2022). "Our results showed that tumor exo-NAC or exo-miR-155-5p decreases CXCL10 and CCL2 expression levels in macrophages." (PMID 35086548, 2022). "One specific immunotherapy strategy is the blockade of CCL2/MCP-1 (monocyte chemoattractant protein-1), an elevated cytokine during CRC progression which recruits monocytes to the tumor microenvironment." (PMID 35461243, 2022). "Regarding cancer progression, disruption of the endothelial barrier by tumor-derived secreted factors, such as VEGF and CCL2, is a critical step in cancer cell extravasation." (PMID 35237673, 2022). "LncRNA-LNMAT1 induces the upregulation of CCL2 and recruits a large number of macrophages into tumor cells, which then promotes the secretion of VEGF-C and enhances tumor metastasis." (PMID 36601121, 2022). "In BlCa, IL-6, CCL2, CXCL1, CXCL12, IL-8 and TGF-β1 play putative roles in promoting tumor progression, growth, invasion, and metastases formation." (PMID 36699696, 2022). "Studies of multiple tumor types including breast cancer, ovarian cancer, and NSCLC have shown that the aggregation of macrophages is positively correlated with CCL2 levels." (PMID 35582531, 2022). "SHP has also been shown to play a partial tumor-suppressive role, because FXR-mediated transcriptional activation of SHP inhibits the expression of cyclin D1 and C-C motif chemokine ligand 2 (CCL2), reducing the proliferation and invasion of tumor cells." (PMID 36278234, 2022). "Several studies emphasized the role of CCL2 in the GBM tumor microenvironment and in chemotaxis of tumor-supporting immune cells." (PMID 35562953, 2022). "Inflammatory monocyte mobilization decreases patient survival, and targeting the CCL2/CCR2 or CSF1/CSF1R axis that allows targeting macrophages or myeloid cell lineages improves chemotherapeutic efficacy and anti-tumour T-cell response." (PMID 36077801, 2022). "CCL2, CCL3, CCL5, and CCL7 attract monocytes/macrophages to exert anti-infective, anti-tumor, and immunomodulatory effects at sites of inflammation." (PMID 36188003, 2022). "Generally, CCL17 weakly and positively correlated with early factors of tumour grow (CXCL10), but then weakly and negatively correlated with late factors of tumour growth (myeloid cell populations); CXCL1 and CCL2 acted like CCL17 in this respect." (PMID 35226704, 2022). "Consistent with the changes in serum CCL2 and CCL5 in tumor-bearing mice, there were corresponding changes in ZO-1, Occludin and phosphorylated p38 protein levels in these premetastatic mouse lungs." (PMID 36438499, 2022). "Previous studies have suggested that many chemokines (CCL5 and CCL2) and cytokines (the VEGF family members and CSF‐1) can be able to recruit circulating inflammatory monocytes to the tumor environment, exerting an enormous effect on the formation of TAMs." (PMID 35593325, 2022). "The CCL2/CCR2 axis is implied in the proliferation, invasion, and angiogenesis of tumor cells and recruitment of immunosuppressive cells." (PMID 35702353, 2022). "Consistent with previous studies, DDR can lead to the production of cancer-related inflammation, which induces TME-secreting factors such as TNF, IL-1, CCL2, and CXCL8; and activates transcription factors of NF-Κb, Stat-3, thus promoting tumor proliferation." (PMID 35413945, 2022). "Since chemokines, such as CCL2 and CXCL12, can regulate tumor behavior similar to metastasis, their levels were also determined." (PMID 36012284, 2022).
tumor (continued). "The chemokines CCL-2 and CCL-5 attract macrophages into the tumor and lead to tumor progression and metastasis." (PMID 36611932, 2022). "On the other hand, myeloid derived suppressor cells are recruited by CCL-2, CXCL-5, CXCL-8 and CXCL-12 into the TME, building a tumor-promoting and immune-suppressive microenvironment." (PMID 36611932, 2022). "Among CCL chemokines, CCL2, 3, 4, 7, and 8 were significantly less secreted by tumor tissues, while CCL17, CCL20, and CCL22 were secreted in higher concentrations in tumor as compared to juxta-tumor tissues." (PMID 36539890, 2022). "We showed that KRAS-mutant tumor cells exclusively respond to KRAS blockade in vivo, because the oncogene co-opts host myeloid cells via a C-C-motif chemokine ligand 2 (CCL2)/interleukin-1 beta (IL-1β)-mediated signaling loop for sustained tumorigenicity." (PMID 35327394, 2022). "In in vivo experiments, using a xenograft mouse model of human MLS, a marked reduction of human CCL2, CXCL8 and PTX3 after trabectedin administration was observed, demonstrating that this effect on tumor cells occurs also in vivo." (PMID 35299737, 2022). "Mechanistically, PADC cells elevate the production of CCL2 chemokine to attract CCR2+ M2-like macrophage infiltration, which reciprocally provides tumor cells with abundant TGFβ to promote KRAS-independent tumor growth." (PMID 36230914, 2022). "Blocking the CCL2/CCR2 axis was reported to be effective in reducing MDSCs and tumor growth in different preclinical models." (PMID 35158779, 2022). "Conversely, isolated MES cells intrinsically express CCL2 and PDCD1LG2, which can facilitate a pro-tumor microenvironment by attracting monocytes and inhibiting T-cell proliferation/cytokine production, respectively." (PMID 35810190, 2022). "Mechanistically, when these mast cells migrate to tumors, they augment the interaction between estrogen receptors (ERs) and C–C Motif Chemokine Ligand 2 (CCL2), with CCL2 promoting EMT and matrix metalloproteinase (MMP) synthesis at the tumor site." (PMID 36140470, 2022). "The signaling of CCL2/CCR2 is well known to promote macrophage infiltration and activation, consequently contributing to tumor growth and progression." (PMID 35094142, 2022). "CDH17 ‘high-methylation’ cases, showed increased expression of IL12B, IL10, CXCL9 and 10 and CCL2 compared to CDH17 ‘low-methylation’ cases, suggestive of a favourable cytokine/chemokine ‘milieu’ in these tumours." (PMID 36612154, 2022). "CCL2 and CCL5 are responsible for the recruitment of macrophages into the tumor microenvironment and tumor development." (PMID 35677043, 2022). "When the production of reactive nitrogen species is inhibited, the CCL2/CCR2 pathway is working to allow CD8 T-cell recruitment and tumor growth control." (PMID 36429101, 2022). "In TME, TAMs and some tumor-derived vascular growth factors such as VEGF, PDGF, CCL2, and CCL8 promote tumor neovascularization and maintain the tumor growth vascular network." (PMID 35681736, 2022). "Once in the site, MDSCs stimulate the migration of tumor cells by secreting TNFα, CXCL2, TGFβ, IL-6 and CCL2." (PMID 35158779, 2022). "The inhibition of other TAM-recruiting chemokines such as CCL2 and CXCR4 resulted in decreased tumor growth and progression in preclinical trials; however, their performances in combination with ICIs have not yet been evaluated." (PMID 35345849, 2022). "For example, bindarit is used to inhibit CCL2, and monoclonal antibodies that block VEGFR2 reduce macrophage infiltration and tumor growth." (PMID 35582531, 2022). "N2 type can promote the progression of tumors by expressing vascular endothelial growth factor and a variety of chemokines (CCL2, CCL5, etc.), can inhibit the anti-tumor activity of other immune cells, and can form cell clusters with circulating tumor cells." (PMID 36034356, 2022).
tumor (continued). "In parallel, treatment of the tumor cells by i-Ras also led to a reduction of their extracellular levels: 35–40%, 90–95% and 75–85% inhibition of CXCL8, CCL2 and CCL5, respectively." (PMID 35205789, 2022). "Mechanistically, we show that Gata4-dependent tumor suppression requires cytotoxic CD8 T cells and partially requires the secreted chemokine CCL2." (PMID 35017504, 2022). "Chemokine MCP-1 and CCL2 synthesis, produced by both tumor and stromal cells, mediates the recruitment of C-C chemokine receptor 2 (CCR2) monocytes (receptor for CCL2) and their subsequent differentiation into metastasis-associated macrophages (MAMs)." (PMID 36294305, 2022). "Exosomal miRNA often targets distinct pathways such as CCL2, IL-6, IL-8, WNT, and PI3K and remodels the pro-malignant properties of tumor cells." (PMID 35327514, 2022). "Their research proved that LKB1 regulates CCL2 production by triggering the AMPK pathway, which leads to increased macrophage migration to the tumor microenvironment." (PMID 35408440, 2022). "CC-chemokine ligand 2 (CCL2)/Monocyte chemoattractant protein-1 (MCP-1) has been shown to mediate TAM recruitment, and indirectly promote tumor growth and progression." (PMID 35565348, 2022). "CCL2 also promotes cancer cell migration and invasion by activating the p38 MAPK pathway, leading to tumor metastasis." (PMID 35281057, 2022). "Several chemokines (CCL2, CXCL1, CXCL2, CXCL10) were also increased in MC38 and CT26-conditioned media and tumor-bearing mouse serum." (PMID 35962398, 2022). "When a tumor develops, it can recruit and induce macrophages in the TME with various chemokines and cytokines, such as CXCL12, CCL2, GM-CSF, colony-stimulating factor 1 (CSF-1), and IL-3." (PMID 35205732, 2022). "CCL-2 is an HDAC-regulated chemokine, with a pivotal role in facilitating the generation of a tumor-permissive and immune-suppressive microenvironment, via the accruement of myeloid immunosuppressive cell populations." (PMID 35409020, 2022). "Increased levels of CCL2, CSF1, and VEGF-A are correlated with macrophage accumulation at the tumor site in a wide spectrum of human cancers, including those of breast, prostate, ovarian and lung." (PMID 34771482, 2021). "TAMs produce chemokines such as CCL2 and CCL20, which recruit these cells into the tumor microenvironment." (PMID 34178692, 2021). "To overcome this problem, we proposed to exploit this behavior by using three chemoattractants: CXCL10, CCL2 and CCL11, released by a biodegradable hydrogel (GlioGel) to produce a migration of tumor cells toward a therapeutic trap." (PMID 34830041, 2021). "MSCM1-CM, in a CCL2-dependent manner, elicited the accumulation of CCR2-expressing M1 macrophages in tumor tissue." (PMID 34830312, 2021). "MDSCs are the precursor cells of bone marrow-derived DCs, macrophages and granulocytes, recruited to tumor foci by chemokines like CCL2 and CCL5 to perform tumor immunosuppressive function, together forming an immunosuppressive tumor myeloid microenvironment." (PMID 34625124, 2021). "Several of these chemokines, including CCL21, CCL2, and CCL4, recruit anti-tumor leukocytes but can also recruit pro-tumor leukocytes such as Tregs, depending on the type of malignancy." (PMID 34316327, 2021). "In contrast, M2 TAMs release immunosuppressive cytokines, such as CCL2, CCL17, CCL18, CCL22, and CCL24 which drive a reduction of cytotoxic T cell activation and proliferation to promote tumor progression." (PMID 35127700, 2021). "CCL2 via its receptor CCR2 controls the migration of regulatory T cells (Treg) and myeloid suppressor cells, as well as their ability to promote tumor growth." (PMID 34504786, 2021).
tumor (continued). "A few CC chemokines like CCL-2, 11, 16, 18 along with CXCL-18 push endothelial cell endurance and tumour angiogenesis." (PMID 34336101, 2021). "Estrone more effectively raised levels of mRNAs for CCL2 and IL-6 in MCF7 cells pretreated with TNFα than 17β-estradiol, which was validated in MCF7 tumor-bearing mice treated with estrone." (PMID 34359625, 2021). "In fact, TAM and osteoclasts are recruited by tumor-derived inflammatory cytokines and chemokines (TNF-α, CCL2, CCL5) upon EMT activation and during metastatic outgrowth." (PMID 34064859, 2021). "Altogether, CCL2 and its receptor CCR2 are upregulated in tumours and engaged in tumour metastasis through the induction of EMT, the promotion of tumour cell extravasation and the establishment of a PMN." (PMID 34464477, 2021). "For instance, we detected an increase in CCL2, CCL22, and CCL24 levels in all tumor spheroids upon monocyte addition." (PMID 34451433, 2021). "Since pre-treatment with anakinra significantly reduced the levels of chemokines (CXCL8 and CCL2) in both FaDu and UPCI-SCC90 tumour-stromal models, we reasoned that these anakinra-treated tumour-stromal models would therefore also recruit fewer leukocytes." (PMID 35047989, 2021). "Monocytic recruitment to the TME is often mediated by tumor-secreted soluble factors, such as CSF1 and CCL2." (PMID 34789744, 2021). "Next, we resorted to the transplantable Hepa1-6 tumor models to confirm the relevance of SNS/β-ARs signaling and CCL2 regulations." (PMID 34593796, 2021). "Other chemokines, such as CXCL1, 8, 12, 13, and CCL2, 5 produced by TAM, help with the angiogenesis switch in tumor tissues." (PMID 33418996, 2021). "For example, by blocking the most common CCL-2 and CCR-2 signaling pathways, macrophages recruitment and infiltration can be decreased, and tumor development can be delayed." (PMID 34922542, 2021). "Mechanistically, aHSC showed an upregulation of CCL2 when co-cultured with CCR2+ monocytes, a myeloid cell responsible for reprogramming towards an M2 immunosuppressive and tumor-promoting phenotype." (PMID 35008212, 2021). "CCL2 knockout, which is pivotal in attracting and promoting differentiation of peripheral monocytes into TAM, significantly reduced tumor growth." (PMID 34831048, 2021). "This is in line with reports that identified CCR2 ligand CCL2 and CCR5 ligand CCL5 as the main factors, driving M-MDSC migration to the tumor in vivo." (PMID 33578808, 2021). "CCL2 was a common chemokine that recruits monocytes, memory T cells, and dendritic cells during tumor progression through the CCL/CCR2 and CCL2/CCR4 signaling." (PMID 34580284, 2021). "Meanwhile, the CD8+T cell/MDSC ratio was increased within tumours derived from CCL2 deletion mice, and elevated levels of CD8+ T cells restored anti‐tumour immunity to inhibit tumour development." (PMID 34464477, 2021). "In keeping with the effect of EZH2 inhibition in tumor cells, Mo-TAMs from EPZ-6438-treated MCS also showed a significantly enhanced expression of CCL2 and VEGF, thus suggesting a potentiation of the circuits favoring TAM accumulation." (PMID 33922336, 2021). "MCP-1 (CCL2) and IL-8 (CXCL8) are chemokines known to allow tumor progression by promoting tumor angiogenesis." (PMID 33863290, 2021). "High CCL2 level also correlated with high CD68 and CD163 staining in tumor tissues, supporting the role of CCL2 in TAM recruitment." (PMID 34572939, 2021). "Several recent studies have focused on CAF-derived CCL2 in the TME and its role in regulating migration and maturation of myeloid-derived cells in various tumor types." (PMID 34386431, 2021). "To confirm the pivotal role of CCL2-CCR2 signaling in the communication between tumor cells and macrophages, we evaluated CCL2, CCR2, and CCR4 expression in the tumor." (PMID 34580284, 2021).
tumor (continued). "Tumor-promoting TAMs, similarly to other TME cells, by the production of tumor-promoting factors, including VEGF, various cytokines (IL-10, CCL2, CCL17, CCL22, TGF-β), and matrix-degrading enzymes, facilitate the tumor invasion, angiogenesis, and spread." (PMID 34885122, 2021). "In the TME, the presence of CAFs and their secretion of chemokines and cytokines such as CCL2, CCL5, CCL17, IL-1, IL-6, IL-13, and IL-26 can favor a tumor-promoting Th2 and Th17 immune response, at the expense of tumor-protective Th1 responses." (PMID 34663337, 2021). "Hereby, centering on CCL2 in PDAC, we demonstrated that CCL2 manifests as a pro‐tumoral factor that modulates M‐MDSC recruitment and functionality and rears a tumor‐tolerant immune microenvironment." (PMID 34525267, 2021). "Furthermore, analysis of 366 HCC tumor samples from TCGA demonstrated positive associations of tissue CRP level and genes related to myeloid cells, including CD68 and CD14, as well as chemokines and receptors for the chemotaxis of monocytes or neutrophils, such as CCL2, CCR2, and CXCL1." (PMID 35070979, 2021). "It is well known that CCL2, CCL5, CXCL12 and CXCL16 produced by the tumor are crucially involved in the tropic process of BM-MSCs." (PMID 34513701, 2021). "CHI3L1 up-regulates pro-inflammatory mediators, CCL2, CXCL2 and MMP-9, all of which contribute to tumor growth and metastasis, and treatment with chitin can significantly reduce these effects." (PMID 33937022, 2021). "ECs can influence ECM remodeling either by the expression of MMPs such as MMP2 and MMP9 or by the release of cytokines like CCL2, IL-8 and CXCL16, which act in a paracrine manner by upregulating the expression of MMPs in other cell types, such as tumor cells." (PMID 34073394, 2021). "For example, CCL-2, an important SASP factor secreted by senescent cells, attracts MDSCs to the tumor site." (PMID 34746270, 2021). "The chemokine CCL2 and its receptor CCR2 act a pivotal part in tumor invasion and metastasis by recruiting TAMs." (PMID 33391402, 2021). "It targets upregulation of CCL-2/CCR-2 and CXC3CL-1/CX3CR-1 axis in macrophage-tumour cell crosstalk." (PMID 34336101, 2021). "Upon chemical and irradiation exposure, surviving cancer cells produce pro-tumor cytokines as IL-17, stromal cell-derived factor-1 (SDF-1), CCL2, and colony-stimulating factor 1 (CSF-1), which limit the therapeutic benefits." (PMID 33800829, 2021). "MSCs promptly migrate into tumor sites in response to chemokines, such as CCL2, CCL5, CXCL12, and CXCL16, and are expanded by cytokines, such as TGFβ, VEGF, FGF, and IGF, all of which are released from the tumor milieu." (PMID 33535613, 2021). "More importantly, TA-MSCs can recruit macrophages and myeloid-derived suppressor cells (MDSCs) into the tumor microenvironment through CC-chemokine receptor 2 (CCR2) ligands, including CC-chemokine ligand 2 (CCL2), CCL7, and CCL12." (PMID 33889575, 2021). "Among these, CCL2 (referred to as monocyte chemo-attractant protein-1, MCP-1) is the most important in tumor progression." (PMID 33840390, 2021). "On the contrary, several sets of chemokines and their receptors, such as CCR2/CCL2, CXCR2/CXCL5, and VEGF, have been reported to promote tumor progression in other tumors by enhancing immunosuppressive M2-TAM and MDSC function." (PMID 34200100, 2021). "Using immunofluorescence (IF) staining of tumor sections from EPN and AEP patients, we confirmed the presence of CCL2+ TAMs and CD44+ TAMs as subgroups and observed higher proportions of these two TAM subsets in AEP." (PMID 34824203, 2021). "CCL-2 and CXCL-12 can aid in angiogenesis and impede endothelial cells' apoptosis through straight receptor (CXCR-4 and CCR-2) binding on tumour vessels or obliquely propping up drafting in leukocytes." (PMID 34336101, 2021).